SCYGR7 (small cysteine and glycine repeat containing 7)
Description:
In the hair cortex, hair keratin intermediate filaments are embedded in an interfilamentous matrix, consisting of hair keratin-associated proteins (KRTAP), which are essential for the formation of a rigid and resistant hair shaft through their extensive disulfide bond cross-linking with abundant cysteine residues of hair keratins. The matrix proteins include the high-sulfur and high-glycine-tyrosine keratins.
Synonyms: KRTAP28-7
Gene: Protein-coding gene on chromosome 2 (227,728,335 to 227,728,625, forward strand). Ensembl gene ENSG00000284718.
Homologues: Paralogues in human: SCYGR3 (96% identical).